SIRT1 (sirtuin 1)
Diseases named in the same sentence as SIRT1 in open-access papers (continued):
Sharing a sentence is not in itself a finding about the gene and the disease.
memory impairment (26 papers, 2015 to 2025). "SIRT1 overexpression is associated with reduced learning and memory impairments, suggesting a neuroprotective role of SIRT1 in cognitive function." (PMID 40103671, 2025). "Importantly, the observed linagliptin-induced amelioration of learning and memory impairment was associated with SIRT1/Nrf2/HO-1 axis stimulation." (PMID 37630980, 2023). "In addition, decreased SIRT1 levels can also increase the release of inflammatory mediators by microglia, which infiltrate into the white matter, causing damage and neuronal loss and resulting in learning and memory impairment." (PMID 37718350, 2024). "The drug mitigates AD pathology and associated symptoms, such as memory impairment, by fostering glycolysis through the GLP-1/SIRT1/GLUT4 pathway." (PMID 38921025, 2024). "SIRT1 is well known as an antagonist of neurodegenerative processes and thereby inhibits cognition and memory impairment." (PMID 32727328, 2021). "In summary, we can conclude that 17β-estradiol, in an ERα/SIRT1-dependent manner, abrogates d-gal-induced oxidative stress–mediated memory impairment, neuroinflammation, and neurodegeneration in adult mice." (PMID 31430865, 2019). "SIRT1 is crucial for synaptic plasticity in neurons and memory function, and also induces neuronal protection in neurodegenerative diseases and memory impairment." (PMID 31430865, 2019). "Collectively our results suggested that Fisetin may attenuate oxidative stress, neuroinflammation, neurodegeneration, and memory impairment in D-gal-treated mice via regulation of SIRT1, Nrf2/HO-1, and p-JNK/NF-kB-mediated neuroinflammation." (PMID 33716741, 2021). "Decreased SIRT1 in the hippocampus might contribute to age-related memory impairments, as transgenic mice with SIRT1 deletions are impaired in hippocampal-dependent tasks." (PMID 26252151, 2015). "Jenwitheesuk and colleagues suggest that the memory impairment that occurs in aged individuals might be due to diminished circadian expression of melatonin and the resultant effect on hippocampal SIRT1 expression." (PMID 26252151, 2015). "Therefore, the present study aimed to investigate the effects of BHBA on learning and memory impairment with a D-gal-induced injury model and to determine whether SIRT1 mediates these effects through regulating OS and inflammation processes." (PMID 34880753, 2021). "We conducted behavioral tests to determine the involvement of SIRT1/Nrf2/GPx4 signaling in HIBI‐induced learning and memory impairments and assess its relationship to ferroptosis." (PMID 36184790, 2022). "Activation of SIRT1/Nrf2/GPx4 signaling following Res treatment represents a potential therapeutic strategy for inhibiting ferroptosis and ameliorating HIBI‐induced learning and memory impairments." (PMID 36184790, 2022). "It has been shown that mice lacking Sirt1 catalytic activity in the brain develop learning and memory impairment, decreased dendritic spine density and disrupted plasticity, suggesting that Sirt1 plays a critical role in learning and memory." (PMID 33805206, 2021). "Furthermore, in two memory impairment mouse models (aged and APPS1-21), an increase in miR-34c-5p was correlated with decreased SIRT1 protein." (PMID 25755632, 2015).
osteosarcoma (26 papers, 2012 to 2025). A usually aggressive malignant bone-forming mesenchymal neoplasm, predominantly affecting adolescents and young adults. "In osteosarcoma patients high expression of SIRT1 is associated with poor prognosis suggesting that SIRT1 promotes autophagy." (PMID 31608237, 2019). "High expression of SIRT1 was linked to high risk osteosarcoma patients, however, SIRT1 expression has also been reported to be down-regulated in metastatic osteosarcoma." (PMID 31608237, 2019). "SIRT1 expression was significantly upregulated in high-risk patients with osteosarcoma compared with that of low-risk patients in the GSE21257 dataset using SurvExpress analysis (p = 1.15 × 10−11)." (PMID 27793039, 2016). "We reported for the first time the association between increased SIRT1 expression and poor prognosis in patients with osteosarcoma." (PMID 27793039, 2016). "Taken together, these results suggest that high SIRT1 expression is clearly associated with the metastatic potential of human primary osteosarcoma cells." (PMID 27793039, 2016). "Here, we report that SIRT1 modulated osteosarcoma metastasis by regulating expression of metastatic-associated genes." (PMID 27793039, 2016). "To better understand the relationship between SIRT1 and osteosarcoma metastasis, we analysed several primary osteosarcoma tissues from patients and investigated the association between SIRT1 and osteosarcoma metastasis in vivo and in vitro." (PMID 27793039, 2016). "In human osteosarcoma cells, SIRT1 expression level may be coupled with metastatic risk in patients with osteosarcoma." (PMID 38726050, 2023). "The SIRT1 protein was significantly upregulated in most primary osteosarcoma tumours, compared with normal tissues, and the SIRT1 expression level may be coupled with metastatic risk in patients with osteosarcoma." (PMID 27793039, 2016). "Furthermore, we analysed the association between SIRT1 expression and progression in patients with osteosarcoma; stronger SIRT1 expression was significantly correlated with a higher metastatic rate." (PMID 27793039, 2016). "The published article titled “MicroRNA-133b Inhibits Cell Proliferation and Invasion in Osteosarcoma by Targeting Sirt1” has been retracted from Oncology Research, Vol." (PMID 41179297, 2025). "We compared the autophagy levels in osteosarcoma cells with SIRT1 overexpression to those with SIRT1 knockdown, revealing decreased autophagy levels in cells where SIRT1 was knocked down." (PMID 39877461, 2025). "We also found the high expression of some autophagy-promoting genes, such as SIRT1, indicating the activation of autophagy in osteosarcoma cell lines overexpressing EWSR1-PSMC5 fusion genes." (PMID 39877461, 2025). "Specifically, SIRT1 is reported to play a distinctive role in osteosarcoma tumors, promoting metastasis, with its inhibition exerting antitumor activity." (PMID 38726050, 2023). "In contrast, the expressions of LMO2, MAML3, and SIRT1 were downregulated in all osteosarcoma cell lines." (PMID 35734428, 2022). "According to Ye dong’s findings, MT treatment inhibits SIRT1 exerting antitumor activity in human osteosarcoma cells, and the results suggested that MT is an inhibitor targeting SIRT1 signaling." (PMID 36235621, 2022). "SIRT1 promotes osteosarcoma metastasis by regulating the expression of genes that are associated with a metastatic phenotype." (PMID 30881341, 2019). "Cell migration and wound-healing assays supported the invasive activity of osteosarcoma cells and downregulating SIRT1 with shRNA inhibition determined that the migration ability of osteosarcoma cells in vitro decreased." (PMID 30881341, 2019). "Consistent with our in vitro data, SIRT1 knockdown inhibited lung metastasis of osteosarcoma cells in vivo." (PMID 27793039, 2016). "We first evaluated the expression levels of SIRT1 in 33 primary osteosarcoma tissues, and their bone tissues, adjacent to the tumour obtained from patients by immunohistochemistry." (PMID 27793039, 2016).
osteosarcoma (continued). "To confirm the key function of SIRT1 in osteosarcoma metastasis, we knocked down SIRT1 in the KHOS/NP osteosarcoma cell line and MDOS-14 primary cells." (PMID 27793039, 2016). "To further address the effect and importance of SIRT1 in osteosarcoma cell migration and metastasis, we knocked down SIRT1 protein expression in osteosarcoma cells using shRNA." (PMID 27793039, 2016). "Most osteosarcoma tumour tissues showed strong or very strong SIRT1 expression, whereas more than half of the adjacent tumour tissue samples did not express SIRT1." (PMID 27793039, 2016). "Here, we report that SIRT1 promotes osteosarcoma metastasis by regulating the expression of metastatic-associated genes." (PMID 27793039, 2016). "In summary, our study revealed, for the first time, a positive correlation between SIRT1 expression and metastatic rate in patients with osteosarcoma." (PMID 27793039, 2016). "To assess the role of SIRT1 in osteosarcoma cells, we further analysed the survival and metastatic rates of 22 patients with osteosarcoma." (PMID 27793039, 2016). "Our data provide evidence for an important role of SIRT1 in promoting the metastasis of osteosarcoma, by regulating transcription of targeted genes." (PMID 27793039, 2016). "Our investigation revealed that SIRT1 was crucial for osteosarcoma cells to migrate, and that deleting SIRT1 efficiently inhibited invasion of osteosarcoma cells." (PMID 27793039, 2016). "Although our results revealed that SIRT1 promoted invasion of osteosarcoma, several other studies have claimed that SIRT1 inhibits tumour progression." (PMID 27793039, 2016). "Lentiviral transduction enabled stable downregulation of SIRT1 compared with that in vector-transduced cells in the KHOS/NP osteosarcoma cell line." (PMID 27793039, 2016). "Given that SIRT1 has been implicated in the modulation of apoptosis, DNA repair, and chemotherapy resistance, the interplay between NNMT and SIRT1 may significantly influence osteosarcoma cell survival." (PMID 40332124, 2025). "In addition to affecting the classical AKT-mTOR signaling pathway, we observed a significant increase in SIRT1 levels in osteosarcoma cells overexpressing the EWSR1-PSMC5 fusion gene, as evidenced by mRNA sequencing." (PMID 39877461, 2025). "Notably, the downregulation of osteosarcoma-supporting genes SIRT1 and Nrf2, as demonstrated in the mechanically treated specimens in the current study, aligns with the compromised protection of SAOS-2 cells induced by mechanical stimulation." (PMID 38726050, 2023). "Of note, SIRT1 has been previously shown to act as a negative regulator of the centriole duplication in a mechanism involving Polo-like and Aurora A kinases in human osteosarcoma cell line." (PMID 37816710, 2023). "Conflicting roles of SIRT1 have been reported in osteosarcoma." (PMID 31608237, 2019). "In this perspective, we emphasize the current advances and interactions involving the insulin/IGF1R, SIRT1, and FOXOs pathways in the bone and osteosarcoma for a better understanding of the mechanisms potentially underpinning tissue degeneration and tumorigenesis." (PMID 30881341, 2019). "Importantly, downregulating SIRT1 with shRNA inhibited the migration ability of osteosarcoma cells in vitro and suppressed tumour lung metastasis in mice." (PMID 27793039, 2016). "To better understand the correlation between SIRT1 expression and the invasion ability of osteosarcoma cells, we chose seven primary osteosarcoma cell samples, cultured from fresh biopsy tissue sections from patients with osteosarcoma, to detect SIRT1 protein expression levels." (PMID 27793039, 2016). "Consequently, these results indicate that the SIRT1 expression was significantly upregulated in most osteosarcoma tissues compared with that of normal tissues." (PMID 27793039, 2016). "Therefore, our study is the first to reveal the important role of SIRT1 in the metastatic potential of osteosarcoma cells." (PMID 27793039, 2016).
osteosarcoma (continued). "In addition, research on Sirt1 in osteosarcoma, particularly osteosarcoma metastasis, remains very limited and there is much that needs to be investigated." (PMID 27793039, 2016). "Therefore, SIRT1 deserves further study as a potential biomarker for diagnosing and predicting osteosarcoma metastasis." (PMID 27793039, 2016). "Further experiments were conducted to determine whether SIRT1 regulates the migration ability of osteosarcoma." (PMID 27793039, 2016). "Therefore, our data suggest that the SIRT1 protein is required for migration of osteosarcoma cells in vitro." (PMID 27793039, 2016). "In summary, high levels of SIRT1 may be a biomarker for a high metastatic rate in osteosarcoma patients; inhibiting SIRT1 could be a potent therapeutic intervention for these patients." (PMID 27793039, 2016). "Our study also indicates a new opportunity to treat osteosarcoma metastasis by targeting SIRT1." (PMID 27793039, 2016). "Our study illustrates that high levels of SIRT1 may be a biomarker for a high metastatic rate in patients; furthermore, inhibiting SIRT1 could be a potent therapeutic intervention in patients with osteosarcoma." (PMID 27793039, 2016). "Moreover, the results of cell migration and wound-healing assays further suggested that higher expression of SIRT1 promoted invasive activity of osteosarcoma cells." (PMID 27793039, 2016). "Similarly, the RES-mediated apoptosis of osteosarcoma cells involves Sirt1 activation." (PMID 36499492, 2022). "In this report, we found that the K7 of Rab22a-NeoF1, acetylated by p300/CBP while de-acetylated by both HDAC6 and SIRT1, plays a key role in its binding to SmgGDS607, and consequently affects its activation of RhoA and promotion of cell migration, invasion and lung metastasis in osteosarcoma." (PMID 32685017, 2020). "Thus, the down-regulation of SIRT1 can be a therapeutic option for treatment of osteosarcoma." (PMID 31798348, 2019). "Thus, we report a crucial function of SIRT1 in osteosarcoma cell metastasis." (PMID 27793039, 2016). "SIRT1, SIRT2, SIRT6 and SIRT7 proteins are mainly localized in the nucleus or cytoplasm and are more likely to play important roles in the development of osteosarcoma." (PMID 36344502, 2022). "By inhibiting both PARP1- and SIRT1-dependent cellular pathways, NMNAT1 inhibition can be a promising new tool in osteosarcoma chemotherapy." (PMID 34445574, 2021). "The effects of silencing of the nuclear SIRT1 vs. the mitochondrial SIRT3 and SIRT5 family members on cell viability were analyzed in the human osteosarcoma (U2OS) and mesothelioma (Mero-14 and REN) cell lines." (PMID 31608237, 2019). "Therefore, SIRT1 may increase the migration capacity of osteosarcoma cells in vitro." (PMID 27793039, 2016). "Moreover, SIRT1 may be a biomarker for diagnosing and predicting osteosarcoma metastasis." (PMID 27793039, 2016). "Thus, we focused on SIRT1 and SIRT2 in this study and detected the expression of these two proteins in hFOB1.19 (human osteoblasts) and several osteosarcoma cell lines MG63, HOS, U2OS and Saos-2." (PMID 36344502, 2022). "SIRT1 displayed cell type specific effects as it exerted pro-death activities in osteosarcoma but not in mesothelioma cells possibly attributed to selective modulation of beclin-1 protein levels in U2OS cells." (PMID 31608237, 2019). "To gain insight into the mechanism of SIRT1 knockdown-induced inhibition of osteosarcoma cell migration, we performed a gene expression analysis with RNA extracted from KHOS/NP cells after they were transduced with shRNAs targeting SIRT1 (#1 and #2) or the scrambled control shRNA." (PMID 27793039, 2016).
osteosarcoma (continued). "Since NNMT-driven SIRT1 activation could potentially counteract HDAC inhibition, future studies should explore whether NNMT inhibitors could enhance the therapeutic efficacy of HDAC inhibitors in osteosarcoma treatment." (PMID 40332124, 2025). "We showed that the expression of SIRT2 but not SIRT1 was upregulated in osteosarcoma cells, which suggests that SIRT2 may contribute to the development of osteosarcoma." (PMID 36344502, 2022). "Interestingly, we also found that SIRT1 expression was not related to the sensitivity of osteosarcoma cells to chemotherapy." (PMID 27793039, 2016). "Therefore, the SIRT1 distributional patterns in all patient samples and the adjacent tumours were analysed: only 1 of 33 osteosarcoma cases (3%) demonstrated no SIRT1 expression in tumour tissues, whereas 29 samples (87.9%) showed intense SIRT1 immunoreactivity." (PMID 27793039, 2016). "However, the expression of SIRT1 protein did not change greatly in osteosarcoma cells, which suggests that SIRT2 may play a more important role than SIRT1 in the development of osteosarcoma." (PMID 36344502, 2022).
type 1 diabetes (26 papers, 2016 to 2025). "Previous observations have shown that resveratrol—a Sirt1-activating compound —improved cardiac geometry in an experimental model of type 1 diabetes." (PMID 37957697, 2023). "The study showed that the levels of sirtuin 1 and sirtuin 3 were lower in peripheral blood samples from patients with type 1 diabetes, T2D, or hypothyroidism than in healthy individuals." (PMID 35373529, 2022). "In the hearts of mice with streptozotocin (STZ)-induced type 1 diabetes, the expression of miR-195 was upregulated while that of miR-195-target proteins (sirtuin 1 [SIRT1] and B cell leukemia/lymphoma 2 [Bcl-2]) was downregulated." (PMID 33819184, 2021). "Treatment with 1,25(OH)2D3 can inhibit PARP1 expression to increase the expression of SIRT1 and repress the phosphorylation of mammalian target of rapamycin (mTOR), which improves cardiac dysfunction, hypertrophy and fibrosis in rats of type 1 diabetes (T1D)." (PMID 33537003, 2020). "This study investigated the effects of type 1 diabetes (T1D), type 2 diabetes (T2D), and HT on the expression levels of SIRT1, SIRT3, and manganese superoxide dismutase (SOD2)." (PMID 30736780, 2019). "Studies of SIRT1 in Type 1 diabetes have to date been mostly confined to its potential role in human autoimmunity with the identification of a gene mutation that gives rise to a monogenic form of the disease." (PMID 30228292, 2018). "Notably, a study involving young women with type 1 diabetes reported SIRT1 levels similar to those observed in healthy individuals." (PMID 41009597, 2025). "Moreover, PPARα agonist was described to prevent fibrosis in the heart of type 1 diabetic mice (T1DM) via the FGF21/PPAR/Sirt1 signaling pathway." (PMID 35677107, 2022). "Sirt1 can greatly attenuate islet α cell hyperplasia in diabetic mice, reduce plasma glucagon concentration, significantly improve blood glucose control and thus treat type 1 diabetes." (PMID 32961025, 2020). "Accordingly, this strategy may offer a new, α-cell centric approach to the treatment of certain patients with type 1 diabetes that complements the role of SIRT1 in preventing organ-specific autoimmunity." (PMID 30228292, 2018). "By reducing the paradoxical increase in glucagon, SIRT1 activation may offer a new, α-cell centric approach to the treatment of type 1 diabetes." (PMID 30228292, 2018). "While cognisant of the complete or near-complete destruction of ß-cells in type 1 diabetes, we nevertheless postulated that SIRT1 may still exert its energy conserving effects in this setting but would need to do so through insulin-independent mechanisms." (PMID 30228292, 2018). "SIRT1 plays a crucial role in Type 1 diabetes mellitus (T1DM), which results from autoimmune-mediated β-cell destruction, leading to insulin deficiency." (PMID 37483618, 2023). "In type 1 diabetic rats, liraglutide inhibits cardiac steatosis, oxidative stress, and apoptosis through activating the activated protein kinase (AMPK)-sirtuin 1 (Sirt1) pathway." (PMID 29440457, 2018). "Using a non-immune mediated streptozotocin model of type 1 diabetes, here we show that administration of an allosteric activator of SIRT1, SRT3025, led to substantial improvement in glycaemic control in the absence of any demonstrable effect on ß-cell mass, insulin secretion or insulin sensitivity." (PMID 30228292, 2018).